TANGO6 (transport and golgi organization 6 homolog)
Synonyms: KIAA1746; TMCO7; FLJ12688
Tractability: Antibody: UniProt predicts a signal peptide or a membrane-spanning region. PROTAC: ubiquitination databases record sites on it; its protein half-life has been measured.
Gene: Protein-coding gene on chromosome 16 (68,843,531 to 69,086,515, forward strand). Ensembl gene ENSG00000103047.
Subcellular location: Membrane
Subcellular location (Human Protein Atlas): Golgi apparatus; Cytosol
Gene Ontology:
Biological process: protein secretion
Cellular component: membrane
Genetic constraint (gnomAD): Loss-of-function variants: 82 observed, 102.51 expected, observed/expected ratio (o/e) 0.8, 90% interval 0.67 to 0.96. The upper end of that interval is the gene's LOEUF score, 0.96, which puts it in group 4 of 6, group 1 being the genes least tolerant of losing a copy. Missense variants: 1,250 observed, 1,304.6 expected, observed/expected ratio (o/e) 0.96, 90% interval 0.91 to 1. Synonymous variants: 471 observed, 507.61 expected, observed/expected ratio (o/e) 0.93, 90% interval 0.86 to 1.
Homologues: Orthologues: chimpanzee TANGO6 (99% identical), macaque TANGO6 (96% identical), dog TANGO6 (84% identical), mouse Tango6 (81% identical), pig TANGO6 (81% identical), guinea pig TANGO6 (80% identical), tropical clawed frog tango6 (52% identical), rabbit TANGO6 (51% identical), zebrafish tango6 (46% identical), Drosophila melanogaster Tango6 (15% identical), Caenorhabditis elegans ekl-6 (15% identical).
Diseases named in the same sentence as TANGO6 in open-access papers:
TANGO6 is named in the same sentence as 8 diseases in open-access papers, as found by Europe PMC text mining. Sharing a sentence is not in itself a finding about the gene and the disease. The quoted sentences say what the papers report.
gastric cancer (1 paper, 2023). A primary or metastatic malignant neoplasm involving the stomach. "Only two HDGC families have been reported to carry large deletions involving specifically CDH1 and TANGO6, both presenting early-onset DGC and gastric cancer in consecutive generations." (PMID 37249750, 2023).
psychosis (1 paper, 2022). "A large-scale GWAS conditioned on DISC1 found eight genes associated with susceptibility to psychosis, among them TANGO6." (PMID 35501310, 2022).
trauma (1 paper, 2022). "However, no known studies have previously reported TANGO6 linked to trauma-related psychopathology." (PMID 35501310, 2022).
TANGO6 also shares sentences with these, for which no sentence is quoted: cancer (1 paper); cervical carcinoma (1); glioma (1); signet ring cell carcinoma (1); tumour (1).